ICAM1 (intercellular adhesion molecule 1)
Diseases named in the same sentence as ICAM1 in open-access papers (continued):
Sharing a sentence is not in itself a finding about the gene and the disease.
macular edema (10 papers, 2010 to 2023). "This study investigated whether soluble intercellular adhesion molecule-1 (sICAM-1) has a role in the pathogenesis of macular edema associated with branch retinal vein occlusion (BRVO) together with vascular endothelial growth factor (VEGF)." (PMID 20738886, 2010). "Therefore, changes of the intraocular ICAM-1 may influence the development of macular edema associated with BRVO." (PMID 20738886, 2010). "Triamcinolone has also been linked to reductions in other inflammatory cytokines, such as IL6, ICAM-1, MCP-1, and PDEF, which have all been implicated in the pathogenesis of macular oedema." (PMID 24527231, 2012). "Thus, the relation between aqueous levels of ICAM-1 or VEGF and macular edema associated with BRVO remain unclear." (PMID 20738886, 2010). "Accordingly, we measured the aqueous levels of soluble ICAM-1 (sICAM-1) and VEGF in BRVO patients with macular edema to investigate the influence of these molecules on macular edema in the setting of BRVO." (PMID 20738886, 2010). "Taken together, our results suggest that nAMD patients had significantly higher intraocular levels of VCAM-1, ICAM-1, CD44 and CD62L and that higher level of VCAM-1 is related to macular fibrosis and increased central retinal thickness (a sign of macular oedema)." (PMID 37985993, 2023). "Proteins such as intercellular adhesion molecule 1 (ICAM1) and monocyte chemoattractant protein 1 (MCP1) which are responsible for recruitment of inflammatory cells are known to be involved in the development of macular edema in RVO and DR." (PMID 28452939, 2017). "We investigated the relations between the aqueous flare value and vitreous levels of vascular endothelial growth factor (VEGF), soluble intercellular adhesion molecule-1 (sICAM-1), and interleukin-6 (IL-6) in patients with CRVO and macular edema or patients with idiopathic macular hole (MH)." (PMID 24325604, 2013).
metastatic melanoma (10 papers, 2011 to 2025). A melanoma that has spread from its primary site to another anatomic site. "Among them, CD8A, SOX2, TYR, CXCL10 and ICAM1 had the most interaction with other proteins associated with metastatic melanoma." (PMID 39820173, 2025). "In an attempt to distinguish the cell adhesion molecules involved in tumor progression and metastasis, researchers have identified the cell surface molecule ICAM-1, as a progression marker for metastatic melanoma." (PMID 21241513, 2011). "Thus, diminished secretion of E/P-selectins and ICAM-1 in the keratinocytes can be related to the inhibition of IL6 secretion observed upon the incubation with metastatic melanoma EVs." (PMID 35327461, 2022). "It was revealed that ICAM-1 expression is higher in metastatic melanoma than in primary melanoma, thus decreasing the expression of ICAM-1 can be hypothesized to yield an antimetastatic effect." (PMID 34068618, 2021). "In line with this, the bioinformatic analysis of the TCGA database revealed that the high expression of the genes coding IL6, IL10, IL12, ICAM-1, ICAM-3, PECAM-1, and CD40L in tissues of patients with metastatic melanoma correlates with the better survival prognosis." (PMID 35327461, 2022). "Coxsackievirus A21 (CVA21, CAVATAK, V937) is an unaltered RNA virus that can selectively infect tumor cells by entry through intercellular adhesion molecule-1 (ICAM-1) and decay-accelerating factor (DAF), which are both overexpressed in metastatic melanoma and other malignancies." (PMID 35227006, 2022). "By using real time PCR we could not demonstrate a clear difference in ICAM-1 mRNA levels between primary melanocytes and primary cultures of metastatic melanoma." (PMID 29245925, 2017).
myocardial ischemia (10 papers, 2013 to 2022). A disorder of cardiac function caused by insufficient blood flow to the muscle tissue of the heart. "They further examined the role of an intravenous miR-141 mimic in a mouse model of myocardial ischemia-reperfusion injury and found that the miR-141 mimic attenuated myocardial ICAM-1 levels and infarction size." (PMID 29720943, 2018). "PPARδ activation inhibited the induction of MCP-1 and intercellular adhesion molecule-1 (ICAM-1) genes in a cardiac ischemia/reperfusion model." (PMID 23607100, 2013). "Although we have revealed and proved that GXNI can play an anti-acute myocardial ischemia-reperfusion injury via inhibiting the CXCR1-NF-κB-COX-2/ICAM-1/VCAM-1-mediated IL-8 signaling pathway, there are still some issues that need to be addressed by further investigation." (PMID 36325326, 2022). "During myocardial ischemia-reperfusion, cardiomyocytes release IL-6, which induces neutrophils and cardiomyocytes to express CD11b/CD18 and intercellular adhesion molecule-1 (ICAM-1), thereby damaging the myocardium." (PMID 34504432, 2021).
neuroblastoma (10 papers, 1993 to 2026). Neuroblastoma (NB) is the most common solid, extracranial childhood tumor. "Blocking lymphocyte function-associated antigen 1 (LFA-1, formed by CD11a and CD18), the ligand of ICAM-1, prevented cytokine-induced neutrophil adhesion to neuroblastoma cells." (PMID 38087370, 2023). "Two studies showed that cytokines like tumor necrosis factor alpha (TNFα), Interleukin (IL)-1 and interferon gamma (IFNγ) induce neutrophil adhesion to SK-N-SH and LAN-1 neuroblastoma cell lines by upregulating intercellular adhesion molecule-1 (ICAM-1) expression." (PMID 38087370, 2023). "We find that LFA-3 (CD58), the ligand for CD2 is of predominant importance in predicting susceptibility of neuroblastoma to the cytotoxic actions of NK and LAK cells, while expression of ICAM-1 (CD54) may also modify susceptibility." (PMID 8494726, 1993). "Sage even increased MCP-1, IL-6, IL-8 and ICAM-1 highly significantly in neuroblastoma (SK-N-SH) cells in a non-IL-1β treated group in 4 h and MCP-1 and ICAM-1 in 24 h." (PMID 39408750, 2024).
pancreatitis (10 papers, 2012 to 2026). Inflammation of the pancreas. "And treatment of rats with mast cell stabilizer cromolyn sodium has been shown to greatly reduce the expressions of ICAM-1 in the lungs in pancreatitis-associated lung injury and decreased IL-6 release." (PMID 26246867, 2015). "And treatment with mast cell stabilizer cromolyn sodium can reduce the expressions of ICAM-1 in the lungs in a rat model of pancreatitis-associated lung injury and downregulate IL-6 level." (PMID 24369442, 2013). "Immune cell infiltration of lung tissue during experimental pancreatitis has been shown to be accompanied by enhanced expression of endothelial adhesion molecules, such as intercellular adhesion molecule-1 (ICAM-1)." (PMID 28144242, 2017). "Mice lacking ICAM-1 are partially protected from cerulein-induced pancreatitis, but the administration of anti-ICAM-1 antibodies had only little effect." (PMID 23372751, 2013). "In summary, this work suggests that zerumbone attenuates the severity of acute necrotizing pancreatitis and pancreatitis-induced hepatic injury, through inhibiting NF-κB activation and downregulation of intercellular adhesion molecule-1 and Interleukin-1β." (PMID 22529518, 2012). "The present paper suggests that treatment of zerumbone on rat attenuates the severity of acute necrotizing pancreatitis and pancreatitis-induced hepatic injury, via inhibiting NF-κB activation and downregulating the expression of ICAM-1 and IL-1β." (PMID 22529518, 2012). "Other studies showed that downregulation of NF-κB not only inhibited ICAM-1 and IL-1β expression, but also attenuated pancreatic and hepatic injury in pancreatitis." (PMID 22529518, 2012). "Furthermore, blocking pulmonary ICAM-1 expression potentially alleviates lung injury in diet-induced pancreatitis." (PMID 32315984, 2020). "3-AB attenuated the activation of adrenal NF-kB, TNF-α and ICAM-1 in pancreatitis." (PMID 27465581, 2016). "In contrast to ICAM-1, blockade of JAM-C with a neutralizing antibody reduced the severity of cerulein-induced pancreatitis and overexpression of JAM-C on endothelial cells enhanced the cellular infiltration and the acinar cell necrosis." (PMID 23372751, 2013).
vitiligo (10 papers, 2012 to 2024). Generalized well circumscribed patches of leukoderma that are generally distributed over symmetric body locations and is due to autoimmune destruction of melanocytes. "Also, female patients showed an increased expression of ICAM1 as compared to male patients suggesting that females have more susceptibility towards vitiligo." (PMID 24312346, 2013). "Reduced skin ETS-1 and ICAM-1 have been linked in patients with vitiligo, and silencing of ETS-1 using small-interfering (si)RNA reduces levels of ICAM1 transcript and ICAM-1 protein in cultured human melanocytes." (PMID 38984117, 2024). "We have earlier reported the crucial role of TNFA in autoimmune pathogenesis of vitiligo, and we now show the involvement of TNFB and its downstream effector, intercellular adhesion molecule 1 (ICAM1) in vitiligo pathogenesis." (PMID 24312346, 2013). "ICAM1 protein levels are upregulated in vitiligo skin and in melanocytes from perilesional vitiligo skin." (PMID 24312346, 2013). "Comparison of the findings showed significant increase in expression of ICAM1 mRNA in 166 vitiligo patients than in 175 unaffected controls after normalization with GAPDH expression as suggested by mean ΔCp values (p = 0.008)." (PMID 24312346, 2013). "For the first time, we show that TNFB +252A/G and exon 3 C/A polymorphisms are associated with vitiligo susceptibility and influence the TNFB and ICAM1 expression." (PMID 24312346, 2013). "In the present study, we have made an attempt to understand the role of TNFB and ICAM1 in vitiligo pathogenesis." (PMID 24312346, 2013). "Additionally, another group showed expression of ICAM1 in perilesional melanocytes of active patches of vitiligo." (PMID 35372360, 2022). "Moreover, the susceptibility of the disease was also checked based on the gender differences and we found that female patients with vitiligo showed significantly higher ICAM1 expression as compared to male patients (p = 0.006)." (PMID 24312346, 2013). "The present study also showed increased expression of ICAM1 in vitiligo patients suggesting that increased TNFB levels might be responsible for increased ICAM1 expression in vitiligo patients and our results are in concordance with the previous reports." (PMID 24312346, 2013). "The aim of the present study was to determine whether TNFB +252A/G (rs909253) and exon 3 C/A (rs1041981) polymorphisms are associated with vitiligo susceptibility, and expression of TNFB and ICAM1 affects the disease onset and progression." (PMID 24312346, 2013). "Moreover, the study also emphasizes influence of TNFB and ICAM1 on the disease progression, onset and gender bias for developing vitiligo." (PMID 24312346, 2013). "Overall, our findings suggest that the increased TNFB transcript levels in vitiligo patients could result, at least in part, from variations at the genetic level which in turn leads to increased ICAM1 expression." (PMID 24312346, 2013). "It has been reported that increased expression of ICAM1 on the melanocytes enhances T cell -melanocyte attachment in the skin and may lead to the destruction of melanocytes in vitiligo." (PMID 24312346, 2013). "Moreover, the ICAM1 expression was increased in active cases of vitiligo as compared to stable vitiligo suggesting its role in the progression of the disease." (PMID 24312346, 2013). "The increased expression of ICAM-1 on the melanocytes enhances T cell/melanocyte attachment in the skin and thus may result in destruction of melanocytes in vitiligo." (PMID 23284977, 2012). "IFN-γ indirectly increases the expression of intercellular adhesion molecule-1 (ICAM-1) on melanocytes and enhances T cell-melanocyte attachment in the skin and thus establishes a link between cytokine and T cell mediated destruction of melanocytes in vitiligo." (PMID 26442157, 2015).
vitiligo (continued). "Moreover, the increased TNFB levels in patients may lead to increased ICAM1 expression which is probably an important link between cytokines and T cells involved in vitiligo pathogenesis." (PMID 24312346, 2013). "ICAM-1, a glycoprotein which enhances T-cell melanocyte attachment probably induced by TNF-α and IFN-γ, showed higher expression in vitiligo patients, which could represent links between cytokines and T-cell involvement in the pathogenesis of vitiligo." (PMID 36980277, 2023). "Additionally, ligands of β2 integrin like ICAM1 and VCAM1 have also shown constant expression on vitiligo melanocytes." (PMID 35372360, 2022).
Atherosclerotic lesion (9 papers, 2012 to 2025). A lesion associated with atherosclerosis, a multifactorial and multipart progressive disease manifested by the focal development within the arterial wall of lesions, that ranges from the development of a fatty streak, plaque progression, and plaque disruption. "It has been shown that expression of both ICAM-1 and VCAM-1 on intimal and medial SMCs is prominent in fibrous plaques and advanced atherosclerotic lesions and that expression of VCAM-1 correlates with intimal neovessels and mononuclear cell infiltration." (PMID 34604206, 2021). "In ECs, intercellular adhesion molecule-1 (ICAM-1), which is a major adhesion molecule that plays a critical role in the homing of leukocytes to sites of atherosclerotic lesions, is known to be induced by senescence." (PMID 32164764, 2020). "However, TNF-α and IL-1β promote the expression of intercellular adhesion molecule-1 (ICAM-1) and vascular cell adhesion molecule-1 (VCAM-1) in endothelial cells in atherosclerotic lesions." (PMID 23243449, 2012). "Adhesion molecules such as intercellular adhesion molecule (ICAM)-1, E-selectin, and vascular cell adhesion molecule (VCAM)-1 make the endothelium surface more adhesive to leukocytes and facilitate their migration into the vessel wall (including atherosclerotic lesions)." (PMID 29041979, 2017).
atopic dermatitis (9 papers, 2016 to 2025). "Also, ICAM-1, an adhesion molecule known to be induced in atopic dermatitis patients than normal individuals, were down-regulated by KRO-105714 compound in SPC and PHA co-treated PBMCs." (PMID 32514255, 2020). "E-selectin, ICAM-1 (intercellular adhesion molecule-1), and VCAM-1 (vascular cell adhesion molecule-1) play a role in atopic dermatitis (AD)." (PMID 37109462, 2023). "In patients with atopic dermatitis, the concentration of ICAM-1 in the blood is elevated compared with that in healthy individuals, and keratinocytes also exhibit increased expression of ICAM-1." (PMID 41303607, 2025). "Additionally, antihistamine co-administration in patients with atopic dermatitis has been reported to enhance the efficacy of topical immunotherapy by reducing IFN-γ production, ICAM-1 expression in the skin, and substance P levels." (PMID 40786079, 2025).
Autoimmunity (9 papers, 2017 to 2025). The occurrence of an immune reaction against the organism's own cells or tissues. "Altogether, we found deletion of genes associated with autoimmunity mediated early hematopoiesis (e.g. ZEB2) and influenced the inflammatory potential (e.g. ICAM1, LSP1 and PRKCB) of iPSC-derived myeloid cells, coinciding with the expected phenotype." (PMID 35610203, 2022). "A study that used NOD.H2h4 mice suggested that increased autoimmunity in the thyroid triggered by iodine is the result of enhanced ICAM-1 expression on thyrocytes from the generation of excess ROS20." (PMID 29133889, 2017). "Therefore, our data may provide some explanation as to how perturbations to PTPN22 promote autoimmunity later in life, following an alteration of ICAM-1-LFA-1 responsiveness over time, which accumulates to promote the expansion of inflammatory IFNγ responses with aging." (PMID 30054208, 2018).
cholangiocarcinoma (9 papers, 2015 to 2025). A carcinoma that arises from the intrahepatic biliary tree (intrahepatic cholangiocarcinoma) or from the junction, or adjacent to the junction, of the right and left hepatic ducts (hilar cholangiocarcinoma). "Quercetin and EGCG worked synergistically and exerted inhibitory effects on cytokine-mediated upregulation of iNOS (inducible nitric oxide synthase) and ICAM-1 (intercellular adhesion molecule-1) via JAK/STAT cascade in cholangiocarcinoma cells." (PMID 32290543, 2020). "Pretreatment of cholangiocarcinoma cells with quercetin inhibited the cytokine-mediated upregulation of inducible nitric oxide synthase (iNOS) and expression of intercellular adhesion molecule-1 (ICAM-1) in the JAK/STAT cascade pathway." (PMID 27589790, 2016). "Fourteen proteins (6%) were identified as more abundant in cholangiocarcinoma, including such proteins as intercellular adhesion molecule 1, ceruloplasmin, haptoglobulin, complement c3, and -c4b." (PMID 25304323, 2015). "QC-mediated pretreatment of cholangiocarcinoma cells inhibited the JAK/STAT cascade pathway-mediated activation of iNOS and activation of the ICAM-1 (intercellular adhesion molecule-1)." (PMID 36233051, 2022).